SLIT2 (slit guidance ligand 2)
Diseases named in the same sentence as SLIT2 in open-access papers (continued):
Sharing a sentence is not in itself a finding about the gene and the disease.
gastric cancer (11 papers, 2016 to 2025). A primary or metastatic malignant neoplasm involving the stomach. "Additionally, the down-regulated DNAJB4, which is implicated in human gastric carcinomas, and SLIT2, which is involved in pancreatic cancer, are also annotated as tumor suppressors, suggesting their potential roles in UVB-induced skin cancers." (PMID 27829444, 2016). "These N2-type polarized neutrophils transport miR-4745-5p/3911 via exosomes, which inhibit the expression of Slit Guidance Ligand 2(SLIT2) in gastric cancer cells, thereby promoting tumor metastasis." (PMID 40342932, 2025). "SLIT2, an axon guidance protein produced by CAFs, promotes metastasis of gastric cancer cell lines AGS and MKN45 by binding to the roundabout guidance receptor 1 (ROBO1)." (PMID 39850884, 2024). "The authors’ laboratory has led several leading researches that have specifically clarified the upstream mechanisms of SLIT2/ROBO1 in gastric cancer (GC) metastasis." (PMID 37443302, 2023). "USP33 stabilizes Robo1 by reducing the ubiquitination of Robo1, thus is required for the Slit2‐Robo1 signalling in inhibiting gastric cancer cell migration and EMT." (PMID 30896071, 2019). "The function of Slit2‐Robo1‐USP33 signalling on gastric cancer cells migration and epithelial‐mesenchymal transition (EMT) was studied both in vitro and in vivo." (PMID 30896071, 2019). "In gastric cancer specifically, SLIT2 promotes metastasis by activating the kinase NEK9." (PMID 40461943, 2025). "Interestingly, Pou2f2 has been identified in a Nf-kB/Pou2f2/Robo1/Slit2 signaling cascade that promotes metastasis in gastric cancer cells." (PMID 31787878, 2019). "The present study demonstrated that SLIT2, an axon guidance protein, produced by CAFs and promoted gastric cancer (GC) metastasis in two gastric cancer cell lines (AGS and MKN45) by binding to roundabout guidance receptor 1 (ROBO1)." (PMID 37443302, 2023). "Slit2, Robo1 and USP33 expressions were analysed in datasets obtained from the Oncomine database and measured in human gastric cancer specimens." (PMID 30896071, 2019). "To examine the potential role of Slit2 signalling in EMT of gastric cancer, we examined the expression markers in MGC‐803 and BGC‐823 transfected with Slit2 plasmid or control by immunofluorescent microscopy." (PMID 30896071, 2019).
liver fibrosis (10 papers, 2019 to 2024). "This hepatocyte-specific loss of Ccn2/Ctgf affected liver fibrosis since there were significant decreases of Slit2, aSMA and Collagen type I genes at mRNA levels." (PMID 36469291, 2023). "It has been found that ROBO2 membrane receptor can promote the progression of liver fibrosis by activating the PI3K-AKT pathway upon binding to the ligand SLIT2." (PMID 39113997, 2024). "In cardiac and hepatic fibrosis, Slit2/Robo1 signaling significantly upregulates TGF-β1 expression and activates the downstream expression of SMAD2/3." (PMID 39768930, 2024). "In summary, this paper presented a novel interaction between Ccn2/Ctgf and Slit2 during liver fibrosis." (PMID 36469291, 2023). "Collectively, these observations indicated that Ccn2/Ctgf formed complexes with Slit2 and its ectopic expression promoted liver fibrosis." (PMID 36469291, 2023). "This interaction was associated with enhanced Slit2/Robo signaling, HSC activation, and liver fibrosis." (PMID 36469291, 2023). "Activation of the Slit2-Robo1 signaling is critically involved in liver fibrosis by activating HSCs." (PMID 36469291, 2023). "In carbon tetrachloride (CCl4)-damaged mice, Slit2-Robo1 signaling promotes liver fibrosis by activating HSCs." (PMID 37238655, 2023). "Slit2 over expressed mice were much more vulnerable to CCl4-induced liver injury and more easily developed liver fibrosis." (PMID 34604283, 2021). "Former studies found that liver fibrosis was mediated by activating hepatic stellate cells through the Slit2/Robo1 and Slit2/Robo2 signal pathway." (PMID 35111704, 2021). "It is easy to speculate a direct association among Ccn2/Ctgf, integrins, Slit2, and Robo1 as a whole complex on HSC cell surface during liver fibrosis." (PMID 36469291, 2023). "We have recently reported mouse models suggesting that deletion of the profibrotic connective tissue growth factor (Ctgf) gene significantly reduces expression of fibrosis-related genes, such as Slit2, aSMA, and Collagen type I, during CCl4-induced liver fibrosis in mice." (PMID 37238655, 2023). "We also observed that the blocking of Slit2/Robo1 signaling could attenuate phosphorylation of Smad2/3 in a TGF-β-independent way in liver fibrosis." (PMID 31242633, 2019). "Deletion of the Ccn2/Ctgf gene significantly reduced expression of fibrosis-related genes including Slit2, a smooth muscle actin (SMA) and Collagen type I during carbon tetrachloride-induced liver fibrosis in mice and rats." (PMID 36469291, 2023). "This study finds that the expression of SLIT2 and CXCL6 in BA liver is exceptionally high, and it is strongly related to liver fibrosis grade." (PMID 35111704, 2021). "In other cases, such as liver fibrosis, it was necessary for the TSP-1 domain to be combined with the IGFBP and VWC domains to promote the interaction between CTGF and slit guidance ligand 2 (SLIT2) in cultured hematopoietic stem cell (HSC) and fibrotic murine livers." (PMID 38731911, 2024). "Moreover, SLIT2 can act on ROBO1 and ROBO2 receptors and promote liver fibrosis by activating downstream PI3K/Akt signaling." (PMID 37238655, 2023). "In addition, Zeng found that Slit2/Robo2 mediates the development of liver fibrosis and regulates the biological behaviour of HSCs by activating PI3K/Akt signalling pathway in a model of thioacetamide‐induced mouse liver fibrosis." (PMID 34750987, 2021).
pancreatic cancer (10 papers, 2015 to 2024). "SLIT2 is a glycoprotein that binds receptors of the Robo family and provides guidance for cell migration and mutations have been seen in other aggressive tumors such as pancreatic cancer and small cell lung cancer." (PMID 25692060, 2015). "Research has shown that the expression of Slit2 is downregulated in pancreatic cancer tissue, whereas the expression of Robo1 is upregulated." (PMID 38567163, 2024). "In the mouse model of pancreatic cancer, high expression of Slit2 can inhibit the growth of pancreatic tumors, reduce its volume, inhibit tumor invasion of the stomach and duodenum, and inhibit lymphatic metastasis, distant metastasis, and tumor angiogenesis." (PMID 32670371, 2020). "Meanwhile, the authors also confirmed that the expression of Slit2 can inhibit the invasion ability of pancreatic tumors to peripheral nerves." (PMID 32670371, 2020). "However, the nerve axon guidance factor SLIT2 promotes tumorigenesis, angiogenesis and metastasis in many cancer types, including pancreatic cancer." (PMID 34745971, 2021). "Furthermore, it provides rationale to investigate the disruption of the stromal/neural compartment connection with SLIT2/ROBO inhibitors for the treatment of pancreatic cancer recurrence and pain." (PMID 25590802, 2015). "(vi) Finally, we showed that SLIT2 level could influence PANR within endogenous mouse models of pancreatic cancer (pdx1-cre/KrasG12D/Ink4Af/f) and human PDA xenografts in nude mice, as the SLIT2 level correlated with increased intratumoral nerve fiber density." (PMID 25590802, 2015). "Examinations of the SLIT2 and ROBO1 expression levels in 10 pancreatic cancer cell lines revealed that SLIT2 seldom displays high expression in PDAC cell lines, especially in liver metastasis-derived CAPAN-1 and cFPAC-1 cells with relatively high ROBO1 expression." (PMID 36792623, 2023).
breast tumor (8 papers, 2004 to 2024). "Promoter methylation associated with reduced SLIT2 expression was found in 43% of breast tumors." (PMID 16280042, 2005). "SLIT2 was reported to regulate breast tumor growth and metastasis by blocking the expansion of tumor vasculature, and was also reported to be a predictive marker for thyroid cancer." (PMID 37483484, 2023). "SLIT2, which is frequently inactivated in lung and breast tumors, is significantly down-regulated in smokers with expression correlating to that of mir-218." (PMID 20567512, 2010). "We have now demonstrated that SLIT3 5′ CpG island similar to SLIT2 is frequently hypermethylated in colorectal and glioma tumours and less so in breast tumours." (PMID 15534609, 2004). "Additionally, the overexpression of full-length SLIT2 in MCF-7 cells inhibited breast tumor growth in nude mice, even in the presence of estrogen." (PMID 39596804, 2024). "This is a first report showing that Slit2 may inhibit breast tumor growth and progression by modulating BMDM metabolic activity and thereby enhance antitumor macrophages in mice." (PMID 34777365, 2021). "Overall, this is a first report showing that Slit2 may inhibit breast tumor growth and progression by modulating BMDM metabolic activity and thereby enhance antitumor macrophages in TAMs of these mice." (PMID 34777365, 2021). "Importantly, tissue analyses revealed the presence of Slit2-expressing fibroblasts in breast tumor tissue thus validating the relevance of these CAFs in human disease and suggesting Slit2 as a potential effector of this tumor-inhibitory CAF-subtype." (PMID 24734219, 2014). "However, the underlying mechanism by which Slit2 regulates immune cell metabolism, and its subsequent impact on breast tumor growth, has not been elucidated." (PMID 34777365, 2021). "However, CYR61, FLRT2, SLIT2, VNN1, MAP1B, MYLK, and TUBA1A gene expressions were high in normal adjacent tissue in comparison with those in breast tumor tissue." (PMID 39596804, 2024).
cervical cancer (7 papers, 2011 to 2023). A primary or metastatic malignant neoplasm involving the cervix. "Our findings confirm that SLIT2 is methylated in cervical cancer, with 61% of cases having methylation above 15%." (PMID 25826459, 2015). "SLIT2 was reported to be hypermethylated in cervical cancer (62% of cases) and hypomethylated in normal tissue using MSP." (PMID 25826459, 2015). "It had been shown that SLIT2 expression levels were negatively correlated with the incidence of cervical cancer in patients treated with postoperative chemotherapy (CT) or radiotherapy (RT), indicating that SLIT2 may be a potential predictive biomarker." (PMID 37914994, 2023). "Taken together, our findings demonstrated that RA inhibits proliferation, invasion and migration of cervical cancer cells via regulating miR-224-3p/Slit2/Robo1 signaling pathway, which indicates that RA can be an effective drug for CC therapies by targeting miR-224-3p and its downstream effectors." (PMID 33621954, 2021). "The remaining genes (DAPK1, RARB, SLIT2 and WIF1) were evaluated for their ability to identify cervical cancer cases in relation to HPV infection and age." (PMID 25826459, 2015). "We confirmed that DAPK1, RARB, SLIT2, and WIF1 are aberrantly methylated in cervical cancer compared to normal tissue, whereas, APC, CDH1 and FHIT are less commonly methylated." (PMID 25826459, 2015). "Pyrosequencing analysis confirmed earlier studies indicating that DAPK1, SLIT2, WIF1 and RARB genes are common targets for aberrant methylation in cervical cancer." (PMID 25826459, 2015). "Hypermethylation at the promoters of genes (SLIT1, SLIT2, SLIT3, ROBO1, and ROBO3) involved in Slit-Robo pathway resulting in down-regulated gene expression was also indentified in invasive cervical cancer." (PMID 22140553, 2011). "While UNC5 expression in cervical neoplastic tissue is still poorly studied, SLIT2 and SLIT3 have been described to be frequently inactivated (due to DNA methylation or deletion) in invasive cervical cancer, with the frequency showing gradual increase as stage progresses." (PMID 32899940, 2020). "Alterations in DNA methylation of specific genes in cervical cancers, such as DAPK1, RARB, WIF1, and SLIT2, may also occur early in cervical carcinogenesis and should be evaluated." (PMID 25826459, 2015). "Prominent alterations in DNA methylation in cervical cancers, such as shown for DAPK1, SLIT2, WIF1 and RARB, may also be early molecular events in cervical carcinogenesis and using the pyrosequencing assays developed here should be further tested in CIN3 lesions." (PMID 25826459, 2015). "Herein, we identified an epigenetic biomarker panel (DAPK1, SLIT2, WIF1 and RARB) that distinguished cervical cancers from normal cytology samples." (PMID 25826459, 2015).
glioblastoma (7 papers, 2018 to 2024). The most malignant astrocytic tumor (WHO grade IV). "The knockdown of SLIT2 has also been shown to inhibit glioblastoma progression, suggesting its oncogenic roles in cancer." (PMID 37443302, 2023). "In either case, Slit2 levels seem to influence glioblastoma growth and treatment resistance; however, further research is needed to elucidate its exact role." (PMID 36497269, 2022). "In order to find out by which mechanism the proteins Robo1 and Slit2 regulate radiation-induced motility of glioblastoma cells, we investigated the expression of the migration-associated proteins fascin and FAK/pFAKY925 and the EMT marker protein vimentin." (PMID 29864155, 2018). "Using time-resolved videography, it was possible to quantify the migration of the two glioblastoma cell lines U-373 MG and U-87 MG and to correlate it with the level of expression of Slit2/Robo1." (PMID 29864155, 2018). "Using qPCR, the mRNA expressions of Slit2 and Robo1 were quantified in two glioblastoma cell lines (U-373 MG and U-87 MG) with different malignancy characteristics regarding migration and radiation resistance, and the results were compared." (PMID 29864155, 2018). "Radiation-induced changes in motility of glioblastoma cells on the one hand and Robo1- und Slit2-mediated motility changes on the other are potentially regulated by different mechanisms." (PMID 29864155, 2018). "Recombinant Slit2 was demonstrated to induce a repulsive signal on glioblastoma cells in a Boyden chamber assay." (PMID 29864155, 2018). "Slit2 was found to act in different cells of glioblastoma tumors expressing Robo1 and Robo2." (PMID 39456164, 2024). "New studies have shown that Slit2 and Robo1 could play important roles in leukocyte chemotaxis and glioblastoma cell migration." (PMID 29864155, 2018). "Previous data show that Slit2 is clearly expressed in normal cerebral neurons, whereas it is expressed only to a low degree in pilocytic astrocytomas, fibrillary astrocytomas, and in glioblastomas compared to the normal cortex." (PMID 29864155, 2018). "qPCR and immunoblotting experiments in two different glioblastoma cell lines (U-373 MG and U-87 MG) with different malignancy revealed that both Slit2 and Robo1 are significantly lower expressed in the cell populations with the highest motility and that the expression was reduced after irradiation." (PMID 29864155, 2018). "We therefore decided to investigate to what extent Slit2/Robo1 regulates the motility of glioblastoma cells and if this system could influence radiation-induced migration." (PMID 29864155, 2018). "Therefore, we assessed the motility of Slit2 or Robo1 overexpressing glioblastoma cells." (PMID 29864155, 2018). "Therefore, we investigated whether the Slit2/Robo1 complex has an impact on the motility of glioblastoma cells and whether irradiation with therapeutic doses modulates this effect." (PMID 29864155, 2018). "Regarding the effect of radiation on SLIT2 expression, it was reported that it was reduced after UVB irradiation in glioblastoma cell lines (U-373 MG and U-87 MG), determined by qPCR and immunoblotting." (PMID 39596804, 2024). "Also,ZC3H18,SLIT2 CARF,GPATCH4,CAMK2D,BCORL1,ARHGAP4mutations were found in glioblastoma (T03)." (PMID 34430964, 2021).
neuroblastoma (7 papers, 2004 to 2025). Neuroblastoma (NB) is the most common solid, extracranial childhood tumor. "More recently, we demonstrated SLIT2 methylation in neuroblastoma, Wilms’ tumour and renal cell carcinoma." (PMID 15534609, 2004). "Notably, SLIT2 acts as a migration inhibitor in neuroblastoma, whose promoter is found to be extensively methylated." (PMID 40448172, 2025). "We analysed 49 neuroblastomas (NBs), 37 Wilms' tumours and 48 RCC, and detected SLIT2 promoter methylation in 29% of NB, 38% of Wilms' tumours and 25% of RCC." (PMID 14735202, 2004). "In neuroblastomas, methylation of several genes, including MGMT, SLIT2, CD44, FLIP and RASSF1A, has been described." (PMID 17064406, 2006).
hepatocellular carcinoma (6 papers, 2015 to 2023). A malignant tumor that arises from hepatocytes. "Slit2 is often inactivated in cancers with promoter region CpG (cytosine--phosphate diester—guanine) island hypermethylation and allele loss, including lung, breast, cervical, intestinal, and hepatocellular carcinomas." (PMID 31242633, 2019). "Genetic suppression of Slit2 or overexpression of Robo1 in hepatocellular carcinoma promotes tumor growth and metastasis." (PMID 35838343, 2023). "SLIT2 upregulated pathological condition of hepatocellular carcinoma shows a higher expression of ROBO1." (PMID 32760720, 2020). "Moreover, previous studies have confirmed that SLIT2 knockdown can induce the over-expression of ROBO1 in hepatocellular carcinoma." (PMID 37059586, 2023). "Further, SLIT2 and ROBO1 were reported to promote the migration of hepatocellular carcinoma cells." (PMID 37059586, 2023).
lung adenocarcinoma (6 papers, 2014 to 2025). A carcinoma that arises from the lung and is characterized by the presence of malignant glandular epithelial cells. "Compared with normal BEAS-2B cells, the expression levels of GYPC and SLIT2 in four human lung adenocarcinoma cell lines (PC9, A549, H1975 and H1299) were up-regulated, while NME1 expression was down-regulated." (PMID 32795291, 2020). "The data revealed that the levels of SLIT2 and SLIT3 were also significantly lower with fold change of SLIT2 to be 0.14 (p = 1.3 × 10−15) in lung adenocarcinoma tissues when compared to normal lung tissues." (PMID 28830450, 2017). "MiR-218 was generated from pri-mir-218-1, which is located in SLIT2, in non-invasive lung adenocarcinoma cells, whereas its expression was inhibited in aggressive lung adenocarcinoma." (PMID 24705471, 2014). "In lung adenocarcinoma, SLIT2 silencing promotes the proliferation and invasion of cancer cells." (PMID 35996510, 2022).
ovarian carcinoma (6 papers, 2011 to 2026). A malignant neoplasm originating from the surface ovarian epithelium. "Promoter hypermethylation of SLIT2 was identified in 56 out of 66 ovarian cancer samples (84.8%), while reduced SLIT2 expression was observed in 52 cases (78.8%)." (PMID 40362385, 2025). "VEGF and SLIT2 genes play an important role in ovarian cancer angiogenesis." (PMID 30619444, 2018). "Basal SLIT2, SLIT3, ROBO1, ROBO2 and ROBO4 expression was lower in primary cultures of ovarian cancer epithelial cells when compared to normal OSE (P<0.05) and in poorly differentiated SKOV-3 cells compared to the more differentiated PEO-14 cells (P<0.05)." (PMID 22132142, 2011). "The results indicated that the incidence of SLIT2 promoter methylation was 75% in ovarian cancer patients, while no SLIT2 promoter methylation was detected in the control group, highlighting challenges in ​​analytical consistency​​." (PMID 41602395, 2026).